ITLN1 (intelectin 1)
Description:
Lectin that specifically recognizes microbial carbohydrate chains in a calcium-dependent manner. Binds to microbial glycans that contain a terminal acyclic 1,2-diol moiety, including beta-linked D-galactofuranose (beta-Galf), D-phosphoglycerol-modified glycans, D-glycero-D-talo-oct-2-ulosonic acid (KO) and 3-deoxy-D-manno-oct-2-ulosonic acid (KDO). Binds to glycans from Gram-positive and Gram-negative bacteria, including K.pneumoniae, S.pneumoniae, Y.pestis, P.mirabilis and P.vulgaris. Does not bind human glycans. Probably plays a role in the defense system against microorganisms (Probable). May function as adipokine that has no effect on basal glucose uptake but enhances insulin-stimulated glucose uptake in adipocytes. Increases AKT phosphorylation in the absence and presence of insulin. May interact with lactoferrin/LTF and increase its uptake, and may thereby play a role in iron absorption.
Synonyms: INTL; ITLN; LFR; FLJ20022; HL-1; hIntL; HL1; omentin
Tractability: Small molecule: a structure with a bound ligand is known. Antibody: UniProt places it where antibodies can reach, with high confidence; its Gene Ontology location is reachable by antibodies, with high confidence; UniProt predicts a signal peptide or a membrane-spanning region.
Gene: Protein-coding gene on chromosome 1 (160,876,539 to 160,893,012, reverse strand). Ensembl gene ENSG00000179914.
Subcellular location: Cell membrane; Secreted
Subcellular location (Human Protein Atlas): Equatorial segment; Vesicles; Acrosome; Mid piece; Principal piece; Predicted to be secreted
Pathways (Reactome):
Immune System: Antimicrobial peptides
Gene Ontology:
Molecular function: calcium ion binding; identical protein binding; oligosaccharide binding; protein binding
Biological process: positive regulation of D-glucose import; positive regulation of protein phosphorylation; protein homotrimerization; response to nematode
Cellular component: extracellular exosome; extracellular region; receptor complex; brush border membrane; membrane raft; plasma membrane
Genetic constraint (gnomAD): Loss-of-function variants: 22 observed, 30.52 expected, observed/expected ratio (o/e) 0.72, 90% interval 0.51 to 1.03. The upper end of that interval is the gene's LOEUF score, 1.03, which puts it in group 4 of 6, group 1 being the genes least tolerant of losing a copy. Missense variants: 294 observed, 355.46 expected, observed/expected ratio (o/e) 0.83, 90% interval 0.75 to 0.91. Synonymous variants: 119 observed, 129.14 expected, observed/expected ratio (o/e) 0.92, 90% interval 0.79 to 1.07.
Homologues: Orthologues: chimpanzee ITLN1 (97% identical), macaque ITLN1 (92% identical), mouse Itln1 (81% identical), rat Itln1 (76% identical), rabbit ITLN1 (72% identical), tropical clawed frog itln1 (67% identical), tropical clawed frog cgl (61% identical), tropical clawed frog itln1al (58% identical), zebrafish ITLN1 (57% identical), zebrafish si:ch211-194p6.7 (53% identical). Paralogues in human: ITLN2 (84% identical).
Diseases named in the same sentence as ITLN1 in open-access papers:
ITLN1 is named in the same sentence as 108 diseases in open-access papers, as found by Europe PMC text mining. Sharing a sentence is not in itself a finding about the gene and the disease. The quoted sentences say what the papers report.
Obesity (16 papers, 2017 to 2025). Accumulation of substantial excess body fat. "Distribution of genotype variants of CD295 rs6700986 and ITLN1 rs952804 SNPs among obesity/IR factors in BC patients (n = 170)." (PMID 41221514, 2025). "It should be noted that ITLN1 rs952804 mutant CT, specifically the T allele, was related to BC risk, DNA damage, obesity, DM, and IR." (PMID 41221514, 2025). "The latest literature data noted that ITLN1 is associated with the pathology of ovaries, like ovarian cancer and PCOS linked with obesity; interestingly the ovarian cancer cell line treated with ITLN1 metastasis was inhibited." (PMID 38408058, 2024). "Lastly, through Gene Set Enrichment Analysis (GSEA20), we elucidated statistically significant associations of ITLN1 expression with co-expressed genes, associated gene pathways, and biological processes related to obesity." (PMID 39333229, 2024). "We then investigated the association of obesity status, sex, insulin resistance, and weight reduction (after bariatric surgery) on ITLN1 expression." (PMID 39333229, 2024). "Human ITLN1 is implicated in the pathophysiology of both Crohn’s disease and metabolic disease, including obesity and associated type 2 diabetes." (PMID 36072603, 2022). "At present, the evidence on the association of ITLN1 gene with obesity is very poor, with only very few studies published." (PMID 29482534, 2018). "Omentin-1, also known as Intelectin-1 (ITLN1), is an adipokine with plasma levels associated with diabetes, obesity, and coronary artery disease." (PMID 28687077, 2017). "ITLN1, encoding intelectin-1 associated with obesity and hypertension, may drive the processes in AS." (PMID 40017519, 2025). "Furthermore, obesity, pre-diabetic event, and being diabetic, along with IR, were associated with BC cases that were ITLN1 rs952804 mutant CT (p ≤ 0.05)." (PMID 41221514, 2025). "All of these data suggest that ITLN1 may regulate the distribution of adipose tissue and confirm its relationship with insulin resistance, which is often associated with obesity." (PMID 38408058, 2024). "This suggests that described associations between ITLN1 and parameters of obesity and metabolic diseases are caused by obesity-related AT tissue dysfunction and may explain why our data contradict some previous reports." (PMID 39333229, 2024). "We hypothesized that AT ITLN1 expression is associated with serum omentin-1, clinical parameters associated with obesity, and with weight loss after bariatric surgery." (PMID 39333229, 2024). "However the evidence base for an association between circulating ITLN1 and overweight/obesity is weak." (PMID 35186726, 2022). "Moreover, human ITLN1, also known as “omentin,” is a highly abundant mRNA and protein product of visceral adipose and has been implicated in the pathophysiology of obesity and metabolically associated diseases as a “novel-adipokine”." (PMID 36072603, 2022). "Obesity has been linked to lower levels of circulating ITLN1 in several studies." (PMID 35186726, 2022). "Omentin-1, also known as intelectin-1, is abundantly expressed in human visceral adipose tissue and inverse associations between circulating omentin-1 and obesity have been demonstrated, while aberrant serum omentin-1 with either increased or decreased levels has been reported in solid malignancies." (PMID 36553076, 2022). "Moreover, ITLN1 has been implicated in the pathophysiology of obesity and associated metabolic disease." (PMID 36072603, 2022). "Human intelectin-1 is implicated in several disease states, including inflammatory bowel disease, asthma, and obesity; however, its specific functions remain unclear." (PMID 34330944, 2021). "Notably, the plasma level of intelectin-1, as was also the case with adiponectin, decreases in cases of obesity and is associated with insulin resistance." (PMID 28422056, 2017).
Obesity (continued). "Our expression analysis identified a weak positive correlation between serum ITLN1 (Omentin-1) and ITLN1 expression among people with obesity, despite the markedly different expression levels across adipose tissues, which we also observe and corroborate." (PMID 39333229, 2024). "We also investigated the correlation of AT ITLN1 expression with genes related to inflammatory response, lipid metabolism, obesity, and regulation of energy balance." (PMID 39333229, 2024). "Obesity-related adipose tissue dysfunction appears to impair VAT ITLN1 expression upregulation with higher BMI classes and higher degree of obesity." (PMID 39333229, 2024). "We investigate associations between AT ITLN1 (Omentin-1, OMNT1) expression and clinical parameters related to obesity and its comorbidities in three clinically well-phenotyped obesity cohorts." (PMID 39333229, 2024). "In VAT, median gene expression of ITLN1 was 10.65 for people with normal or overweight and 12.30 for people with obesity." (PMID 39333229, 2024). "A higher ITLN1 expression was found in people with obesity versus normal/overweight controls in VAT of both women and men with obesity (adj." (PMID 39333229, 2024). "Intelectin-1 (ITLN1; also Omentin-1, OMNT1) is secreted by adipose tissue (AT) and plays an important role in glucose metabolism regulation, with links to obesity-associated diseases." (PMID 39333229, 2024). "In the present study we generated an Itln1 knockout mouse model and tested the consequences in two in vivo models relevant to ITLN1 in human disease: inflammatory bowel disease and obesity." (PMID 36072603, 2022). "We further characterize the expression of Itln1 and then examine outcomes of its ablation in vivo during experimentally induced colitis and diet-induced obesity." (PMID 36072603, 2022). "Serum ITLN1 concentrations have been evaluated in various disease states, including obesity, where an inverse relationship of ITLN1 concentration with adiposity has been observed." (PMID 36072603, 2022). "Human ITLN1, expressed in visceral adipose, has been identified as a biomarker for obesity and related metabolic dysregulation." (PMID 36072603, 2022). "Omentin-1, also known as intelectin-1, is an adipokine identified in adipose tissue that is also related to obesity and its comorbidities." (PMID 30666216, 2018). "The adipokines, adiponectin, and intelectin-1 (also known as omentin-1), whose levels are decreased in obesity, act as tumor suppressor factors in various cancers." (PMID 28422056, 2017). "BC cases with clinical stage T II and positive LN, as well as tumor histologic grade III, presence of obesity, pre-diabetic events, DM, or IR, were associated with CD295 rs6700986 mutant homozygous (CC) and heterozygous (CT) genotypes and ITLN1 rs952804 mutant CT genotype (p ≤ 0.05)." (PMID 41221514, 2025). "Furthermore, we examined the emerging role of ITLN1 SNP in BC and found that the rs952804 polymorphism was related to BC risk indices (grade III, positive LN involvement) as well as to the presence of obesity, IR, DM, and pre-diabetes." (PMID 41221514, 2025). "To investigate the potential role of mouse Itln1 during diet-induced obesity, we assigned Itln1trap/trap mice and Itln1+/+ littermates to receive either control or one of two western-style diets, with varied amounts of sugar (as sucrose) and saturated fat (as lard)." (PMID 36072603, 2022). "Low ITLN1 levels are a marker of the metabolic effects of obesity and might contribute to a deregulation of the PI3k/Akt pathway." (PMID 35186726, 2022). "Together, these findings demonstrate that ablation of Itln1 in C57BL/6 mice does not result in increased susceptibility to diet-induced obesity." (PMID 36072603, 2022). "It has also been suggested that the relationship between ITLN1 and cancer might be influenced by overweight and obesity." (PMID 35186726, 2022). "For example, the plasma concentration of ITLN1 is reduced in patients with obesity and diabetes." (PMID 28687077, 2017).
Obesity (continued). "In particular, BC cases that were CT for the ITLN1 rs952804 mutant (CT) were significantly associated with tumor clinical stage T II and positive LN involvement, as well as tumor histologic grade III, presence of obesity, pre-diabetic event, DM, and IR (p ≤ 0.05)." (PMID 41221514, 2025). "Our results suggest that Paneth cell derived Itln1 does not influence the onset and progression of diet-induced obesity in mice; however, additional work is required to better understand the potential role of Itln1 in mediating changes in the microbiota associated with high fat/sugar feeding." (PMID 36072603, 2022). "ITLN1 expression was higher in VAT of both women and men with obesity, and with increasing body fat in women." (PMID 39333229, 2024). "Thus, tumor-specific directional changes in circulating ITLN1 levels, local versus global changes in ITLN1, and aggregate views of overweight/obesity or metabolic status in patient groups could lead to misinterpretations of the relationship between circulating ITLN1 and cancer risk or status." (PMID 35186726, 2022). "Omentin-1, also known as intelectin-1 (ITLN1), is a novel adipokine with 313 amino acids; it can be used as a marker of obesity and metabolic disorders, including insulin resistance, diabetes, and metabolic syndrome." (PMID 33579281, 2021). "Thus, the causes of CD295 and ITLN1 genes and their downstream protein products are numerous; therefore, if we detect genetic mutations/polymorphisms in these genes in BC cases with or without obesity, IR, or diabetes, this would direct the treatment plan for a better prognosis." (PMID 41221514, 2025). "Various anthropometric parameters, obesity and diabetes factors, and BC clinical measures, as well as plasma levels of leptin, CD295, and ITLN1, were collected, as was information concerning the SNPs under study and DNA damage parameters for both the BC patients and the healthy controls." (PMID 41221514, 2025). "Furthermore, we found that ITLN1 expression increases with VAT tissue mass, but is affected negatively by increasing AT tissue dysfunction among individuals with unhealthy obesity." (PMID 39333229, 2024). "To further investigate the relationship between ITLN1 expression levels and clinical obesity markers, we studied the gene expression of ITLN1 in SC and VAT across three clinical subcohorts of the Leipzig Obesity BioBank (LOBB)." (PMID 39333229, 2024). "Our data also suggest that higher ITLN1 expression among people with obesity does not lead to ITLN1 serum levels found in lean persons, possibly due to a nonlinear rise of ITLN1 expression with increasing fat mass." (PMID 39333229, 2024). "Furthermore, ITLN1 expression increases with VAT tissue mass, but is negatively affected by AT tissue dysfunction among individuals with unhealthy obesity, corroborated by interplay with genes related to tissue inflammation." (PMID 39333229, 2024). "In summary, the available evidence suggests that circulating ITLN1 may be a marker of metabolic dysregulation rather than overweight/obesity per se." (PMID 35186726, 2022). "Indeed, low circulating ITLN1 levels may be a marker of the metabolic effects of obesity, rather than obesity per se, and might contribute to a deregulation of the PI3K/Akt pathway." (PMID 35186726, 2022). "Mimicking this overall trend, ITLN1 expression was higher in VAT then in SAT, regardless of obesity status." (PMID 39333229, 2024). "This review aims to evaluate the role of ITLN1 in cancer without imposing any inclusion criteria, to examine pro- and anticancer roles for ITLN1 and to discuss whether the relationship between ITLN and cancer is mediated by obesity." (PMID 35186726, 2022).
gastric cancer (14 papers, 2013 to 2025). A primary or metastatic malignant neoplasm involving the stomach. "In gastric cancer, ITLN1 positivity associates with favorable histological features, reduced metastatic potential, and improved overall survival, underscoring its potential use as an immunohistochemical prognostic biomarker." (PMID 41149627, 2025). "Our previous studies have shown the aberrant expression of ITLN1 in gastric cancer specimens, which was significantly associated with tumor progression and patients' outcome." (PMID 25965823, 2015). "Taken together, these data indicate that ITLN1 suppresses the progression of gastric cancer through up-regulation of HNF4α, and is associated with improved survival in patients with gastric cancer." (PMID 25965823, 2015). "Our previous studies have implicated the potential roles of ITLN1 in the aggressiveness of gastric cancer." (PMID 25965823, 2015). "Gain- and loss-of-function studies demonstrated that ITLN1 suppressed the growth, invasion, and metastasis of gastric cancer cells in vitro and in vivo." (PMID 25965823, 2015). "Taken together, these results demonstrated that the expression of HNF4α and ITLN1 was positively correlated and associated with improved survival in clinical gastric cancer cases." (PMID 25965823, 2015). "ITLN1 is an inflammatory factor that may be associated with various tumor diseases, including pleural mesothelioma, gastric cancer, and prostate cancer." (PMID 39399504, 2024). "For instance, prospective cohort trials examining ITLN1 expression in gastric cancer, hepatocellular carcinoma, and colorectal cancer using standardized immunohistochemical protocols are essential for ensuring reproducible and clinically meaningful results." (PMID 41149627, 2025). "Gastric cancer cells overexpressing ITLN1 formed fewer colonies, migrated more slowly in scratch assays, and generated smaller subcutaneous tumors in mice, along with a 70% reduction in lung metastases." (PMID 41149627, 2025). "Regarding gastric cancer, future research priorities include the prospective validation of ITLN1 as a routine prognostic biomarker across diverse patient groups and treatment modalities." (PMID 41149627, 2025). "ITLN1 treatment reduced the proliferation and the migratory ability of gastric cancer cells by upregulating hepatocyte nuclear factor 4α (HNF4a) via increased inhibition of nuclear factor kappa B (NFkB)." (PMID 35186726, 2022). "Zheng and colleagues emphasized that ITLN1 levels were greater in gastric cancer tissue compared with normal gastric mucosa." (PMID 35186726, 2022). "ITLN1 also acts as a tumor suppressor in various cancers, such as gastric cancer, ovarian cancer, neuroblastoma, and colon cancer." (PMID 33579281, 2021). "The aberrant ITLN1 expression has been demonstrated to correlate with clinicopathological features and be a robust predicting indicator for prognosis of gastric cancer patients." (PMID 34217290, 2021). "ITLN1 also carries prognostic value for various malignant tumors, such as colorectal, gastric cancers, and neuroblastoma." (PMID 33392181, 2020). "Matrigel invasion assay showed that gastric cancer cells stably transfected with ITLN1 presented an impaired invasion capacity than mock cells." (PMID 25965823, 2015). "To further explore the impacts of ITLN1 on the aggressiveness of gastric cancer cells, we investigated the effects of ITLN1 knockdown and HNF4α restoration on cultured gastric cancer cells." (PMID 25965823, 2015). "Overall, these results demonstrated that ITLN1 considerably facilitated the HNF4α expression at transcriptional levels in gastric cancer cells." (PMID 25965823, 2015). "Our previous studies have shown that ITLN1 is aberrantly expressed in gastric cancer, and is a potential prognostic factor for predicting the outcome of gastric cancer patients." (PMID 25965823, 2015). "Herein, we investigated the functions, downstream targets, and clinical significance of ITLN1 in the progression of gastric cancer." (PMID 25965823, 2015).